SLC24A5 (solute carrier family 24 member 5)
Description:
Calcium, potassium:sodium antiporter that transports 1 Ca(2+) and 1 K(+) to the melanosome in exchange for 4 cytoplasmic Na(+). Involved in pigmentation, possibly by participating in ion transport in melanosomes. Predominant sodium-calcium exchanger in melanocytes.
Synonyms: JSX; NCKX5; OCA6; SHEP4
Tractability: Antibody: UniProt predicts a signal peptide or a membrane-spanning region.
Gene: Protein-coding gene on chromosome 15 (48,120,990 to 48,142,672, forward strand). Ensembl gene ENSG00000188467.
Subcellular location: Golgi apparatus, trans-Golgi network membrane; Melanosome
Pathways (Reactome):
Disease: Defective SLC24A5 causes oculocutaneous albinism 6 (OCA6)
Transport of small molecules: Sodium/Calcium exchangers
Gene Ontology:
Molecular function: calcium, potassium:sodium antiporter activity; protein binding; calcium channel activity; calcium ion transmembrane transporter activity
Biological process: calcium ion import; monoatomic ion transmembrane transport; calcium ion transmembrane transport; intracellular calcium ion homeostasis; potassium ion transmembrane transport; sodium ion transmembrane transport; transmembrane transport
Cellular component: melanosome; trans-Golgi network; trans-Golgi network membrane; Golgi apparatus; membrane
Genetic constraint (gnomAD): Loss-of-function variants: 38 observed, 42.87 expected, observed/expected ratio (o/e) 0.89, 90% interval 0.68 to 1.16. The upper end of that interval is the gene's LOEUF score, 1.16, which puts it in group 5 of 6, group 1 being the genes least tolerant of losing a copy. Missense variants: 541 observed, 596.16 expected, observed/expected ratio (o/e) 0.91, 90% interval 0.85 to 0.97. Synonymous variants: 215 observed, 217.18 expected, observed/expected ratio (o/e) 0.99, 90% interval 0.88 to 1.11.
Homologues: Orthologues: chimpanzee SLC24A5 (99% identical), macaque SLC24A5 (96% identical), pig SLC24A5 (91% identical), rabbit SLC24A5 (89% identical), mouse Slc24a5 (85% identical), rat Slc24a5 (84% identical), guinea pig SLC24A5 (82% identical), tropical clawed frog slc24a5 (69% identical), zebrafish slc24a5 (67% identical), Drosophila melanogaster CG1090 (37% identical). Paralogues in human: SLC24A3 (39% identical), SLC24A4 (37% identical), SLC24A1 (36% identical), SLC24A2 (36% identical).
Diseases named in the same sentence as SLC24A5 in open-access papers:
SLC24A5 is named in the same sentence as 27 diseases in open-access papers, as found by Europe PMC text mining. Sharing a sentence is not in itself a finding about the gene and the disease. The quoted sentences say what the papers report.
melanoma (9 papers, 2011 to 2023). A malignant, usually aggressive tumor composed of atypical, neoplastic melanocytes. "Thus, SNPs HERC2 rs1129038 and SLC24A5 rs1426654 remained strongly associated with risk for the development of melanoma in a dominant model." (PMID 33167923, 2020). "This study assessed previously reported coding variants in albinism genes (TYR, OCA2, TYRP1, SLC45A2, SLC24A5, LRMDA) and common intronic, regulatory variants of OCA2 in individuals with amelanotic/hypomelanotic melanoma, pigmented melanoma cases and controls." (PMID 32966289, 2020). "to detect and characterize gene-gene interactions among HERC2 (rs1129038), SLC24A5 (rs1426654), and SLC45A2 (rs16891982) in risk of developing melanoma." (PMID 33167923, 2020). "Nevertheless, it should be noted that several known MITF target genes such as MLANA, RAB27a or SLC24A5 were weakly but significantly downregulated in all three melanoma cells, in accordance with the observations of a reduced MITF expression." (PMID 24344100, 2013). "Recent GWAS have unveiled association between SNPs or genetic variants in MC1R, TPCN2, ASIP, KITLG, SLC24A5, TYR, IRF4, OCA2/HERC2, SLC24A4, SLC45A2, TYRP1, and pigmentation as well as melanoma." (PMID 21559390, 2011). "Notably, SLC24A5 and SLC45A2 genes encode for melanosome-associated transporters both involved in melatonin synthesis in melanocytes and melanoma cells." (PMID 37397501, 2023). "SLC24A5 expression has been found to be elevated in melanoma." (PMID 28692664, 2017). "According to these results, the best model for predicting melanoma development was the combination of the three factors (HERC2 rs1129038, SLC24A5 rs1426654, and SLC45A2 rs16891982)." (PMID 33167923, 2020).
oculocutaneous albinism (8 papers, 2019 to 2025). Oculocutaneous albinism (OCA) describes a group of inherited disorders of melanin biosynthesis characterized by a generalized reduction in pigmentation of hair, skin and eyes and variable ocular findings including nystagmus, reduced visual acuity and photophobia. "Specifically, two new genes associated with oculocutaneous albinism (OCA) have been identified: SLC24A5 and C10orf11, referred to as OCA6 and OCA7, respectively." (PMID 40076695, 2025). "In unsolved patients, one patient (P96) with oculocutaneous albinism had a heterozygous c.1025C>T:p.(Ala342Val) variant in the SLC24A5 gene." (PMID 35052368, 2021). "Inactivating mutations in these genes have been reported to cause oculocutaneous albinism (OCA), that is, TYR mutations cause OCA1, SLC45A2 mutations cause OCA4, and SLC24A5 mutations cause OCA6." (PMID 40741336, 2025). "The findings of various studies indicate the important role SLC24A5 has on human skin pigmentation: it regulates human epidermal melanogenesis and related diseases, such as nonsyndromic oculocutaneous albinism." (PMID 32443864, 2020). "Among the ion channel and transporters genes involved in pigmentation disorders three are altered in subtypes of oculocutaneous albinism (OCA) (OCA2, SLC45A2, and SLC24A5, in OCA 2, 4 and 6 respectively)." (PMID 39809949, 2025).
albinism (7 papers, 2020 to 2024). A congenital disorder characterized by partial or complete absence of melanin pigment in the eyes, hair, or skin. "In the Pakistani population, very few cases of albinism are reported causative of SLC24A5 mutations." (PMID 35741834, 2022). "Molecular studies identified seven genes linked to the OCA phenotype (TYR, OCA2, TYRP1, SLC45A2, SLC24A5, C10orf11, and DCT) and one locus (OCA5) in consanguineous and sporadic albinism." (PMID 35741834, 2022). "Autosomal recessive ocular albinism (AROA) is a term that has been used for patients with albinism with an ocular phenotype caused by mutations in TYR, OCA2, TYRP, SLC45A2, SLC24A5, or LRMDA (OCA1-7), but without a clearly defined boundary between calling a phenotype OCA or AROA." (PMID 38555393, 2024).
malaria (2 papers, 2014). Malaria is a serious and sometimes fatal disease caused by a parasite that commonly infects a certain type of mosquito which feeds on humans. "These were rs1426654 in SLC24A5 and rs16891982 in SLC45A2, both associated with light skin pigmentation in individuals with European ancestry and rs2814778 in DARC, which encodes the Duffy blood group antigen O allele and is associated with malaria resistance in Africans." (PMID 24980144, 2014).
ocular albinism (2 papers, 2012 to 2023). Albinism affecting the eye in which pigment of the hair and skin is normal or only slightly diluted. "In addition, we screened SLC24A5 (MIM# 609802), which is responsible for ocular albinism and hypopigmentation in Slc24a5 knockout mice and is known to regulate melanogenesis in humans." (PMID 22734612, 2012).
vitamin D deficiency (2 papers, 2021 to 2023). A nutritional condition produced by a deficiency of VITAMIN D in the diet, insufficient production of vitamin D in the skin, inadequate absorption of vitamin D from the diet, or abnormal conversion of vitamin D to its bioactive metabolites. "Specifically, variants in the SLC45A2 and HERC2-OCA2 loci, together with variants in SLC24A5, were shown to explain a large proportion of variance in skin pigmentation and to associate with vitamin D deficiency in a sample of nearly 600 African Americans." (PMID 37963177, 2023). "The pigmentation-associated allele evolution has been shown to include SLC24A5 and RABGAP1 in a previous study, and RABGAP1 was the signature gene for vitamin D deficiency and skin pigmentation." (PMID 34680925, 2021).
alopecia areata (1 paper, 2022). Loss of scalp and body hair involving microscopically inflammatory patchy areas. "The researchers have shown that the transport protein SLC24A5 induces a significantly higher frequency of CD8 T cell activation in an autoimmune disease like Alopecia areata." (PMID 35922752, 2022).
autoimmune disease (1 paper, 2022). A disorder resulting from loss of function or tissue destruction of an organ or multiple organs, arising from humoral or cellular immune responses of the individual to their own tissue constituents. "Furthermore, the importance of some features like GOLGA8M and SLC24A5 has been stated in the other viral infections or autoimmune diseases." (PMID 35922752, 2022).
hypomelanosis (1 paper, 2013). "In fact, it has been demonstrated that the knockdown of slc24a5 provoked dramatic effects on pigmentation in re-differentiating human epidermal melanocytes causing hypomelanosis." (PMID 23874785, 2013).
lateral sclerosis (1 paper, 2012). Primary lateral sclerosis (PLS) is an idiopathic non-familial motor neuron disease characterized by slowly progressive upper motor neuron dysfunction leading to spasticity, mild weakness in voluntary muscle movement, hyperreflexia, and loss of motor speech production. "Expression of SLC24A5, MMP115, and TYR, and genes for crystalline alphaB (CRYAB), Shikimate 5-dehydrogenase and amyotrophic lateral sclerosis 2 (ALS2) were commonly depressed in AV and CV samples relative to BL controls." (PMID 22500953, 2012).
Marfan syndrome (1 paper, 2012). A disorder of the connective tissue. "None of these FBN1 polymorphisms is sufficiently common to rise to genome wide significance in moderately sized studies, but when several of the polymorphisms are all linked to the reduced freckling phenotype of SLC24A5, then lack of freckles can correlate with Marfan's syndrome." (PMID 23300552, 2012).
melasma (1 paper, 2025). "This study investigates the association between genetic variants in SLC45A2, TYR, HERC2, and SLC24A5 genes and the severity of melasma in women of reproductive age." (PMID 39940926, 2025). "Polymorphisms rs1129038 of the HERC2 gene and rs1426654 (A > G) of the SLC24A5 gene also showed significant associations with melasma, particularly for the CC and GG genotypes, respectively, suggesting their involvement in melasma risk." (PMID 39940926, 2025). "Significant associations were observed for the TYR gene (rs1042602), HERC2 gene (rs1129038), and SLC24A5 gene (rs1426654) polymorphisms, highlighting their potential roles in melasma susceptibility." (PMID 39940926, 2025). "By examining polymorphisms in SLC45A2, TYR, HERC2, and SLC24A5, this pilot study highlights the potential genetic factors that may influence melasma susceptibility and severity in a population with distinct pigmentation characteristics." (PMID 39940926, 2025). "Thus, this study presents a novel investigation into the association of genetic polymorphisms in SLC45A2, TYR, HERC2, and SLC24A5 in African women with melasma, a population that has been under-represented in genetic research on pigmentation disorders." (PMID 39940926, 2025). "Our findings show a significant association between the AA genotype and the GG genotype for rs1426654 of the SLC24A5 gene with melasma (OR = 0.03571; 95% CI: 0.005866–0.3303; p = 0.0010), suggesting that the GG genotype may confer a higher risk for melasma development in women of African ancestry." (PMID 39940926, 2025). "However, despite these limitations, this pilot novel study demonstrates valuable insights into melasma development in women of African descent by exploring the genetic role of specific SNPs (SLC45A2, TYR, HERC2, and SLC24A5) in this under-represented population." (PMID 39940926, 2025).
oculocutaneous albinism type 6 (1 paper, 2025). A form of oculocutaneous albinism characterized by light hair at birth that darkens with age, white skin, transparent irides, photophobia, nystagmus, foveal hypoplasia and reduced visual acuity. "Homozygous or compound heterozygous mutations in the SLC24A5 gene cause oculocutaneous albinism type 6 (OCA6)." (PMID 41002986, 2025).
partial albinism (1 paper, 2022). "For example, SLC24A5, MYEF2, and CTXN2 gene variations have been associated with differences in skin pigmentation, partial albinism, and retinal pigment; SLC12A1 plays a key role in concentrating urine, and its defects result in some Bartter-like syndromes." (PMID 35440892, 2022).
prostate carcinoma (1 paper, 2025). A carcinoma that arises from epithelial cells of the prostate gland. "The SLC24A5 gene encodes a sodium-calcium exchanger associated with pigmentation in zebrafish and humans, possibly by facilitating ion transport in melanosomes, whereas the melanophilin gene (MLPH) plays a key role in melanosome transport and prostate cancer susceptibility." (PMID 40274920, 2025).
X-linked ocular albinism (1 paper, 2019). "Six genes are associated with autosomal recessive OCA (TYR, OCA2, TYRP1, SLC45A2, SLC24A5 and LRMDA), and one gene, GPR143, is associated with X-linked ocular albinism (OA)." (PMID 30679655, 2019).
tumor (3 papers, 2021 to 2024). "The frequency of the derived allele at rs16891982*G (SLC45A2) was 0.7098 (CI 0.5365–0.8476; N = 15) and at rs1426654*A (SLC24A5) 1 (CI 0.8899–1; N = 15); both are associated with skin depigmentation in Europeans54." (PMID 33980902, 2021).
SLC24A5 also shares sentences with these, for which no sentence is quoted: Aland island eye disease (1 paper); autism spectrum disorder (1); autosomal recessive ocular albinism (1); cancer (1); congenital cataract (1); Genetic Disorders (1); Griscelli syndrome (1); lysosome-related organelle disorders (1); Stroke (1); viral infections (1).